DENND10P1 (DENND10 pseudogene 1)
Description:
May be a guanine nucleotide exchange factor (GEF).
Synonyms: HT011; formerly FAM45B; FAM45BP
Gene: Transcribed processed pseudogene on chromosome X (130,495,159 to 130,496,232, forward strand). Ensembl gene ENSG00000221930.
Subcellular location: Late endosome